AURKA (aurora kinase A)
Diseases named in the same sentence as AURKA in open-access papers (continued):
Sharing a sentence is not in itself a finding about the gene and the disease.
breast cancer (continued). "In vivo, AurkA-overexpressing primary breast cancer cells showed higher tumorigenic properties." (PMID 27341528, 2016). "By employing chemical proteomics, structure–activity relationship studies and computational modeling, next to the previously implicated BLBC target AURKA, we identified the kinase SYK as being critically required for the viability of a subset of breast cancer cells." (PMID 25699542, 2015). "Furthermore, it was suggested that AURKA is an essential mediator of chemoresistance in colorectal and breast cancers." (PMID 25987188, 2015). "While interplay between BRCA1 and AURKA-RHAMM-TPX2-TUBG1 regulates mammary epithelial polarization, common genetic variation in HMMR (gene product RHAMM) may be associated with risk of breast cancer in BRCA1 mutation carriers." (PMID 25830658, 2015). "Studies have demonstrated that AURKA overexpression contributes to genetic instability and tumourigenesis by disrupting the proper assembly of the mitotic checkpoint complex and occurs in a high proportion of ovarian, bladder, gastric and breast cancers." (PMID 25253995, 2014). "It has recently been proposed that a three-gene model (SCMGENE) that measures ESR1, ERBB2, and AURKA identifies the major breast cancer intrinsic subtypes and provides robust discrimination for clinical use in a manner very similar to a 50-gene subtype predictor (PAM50)." (PMID 22752290, 2012). "Other studies have assessed the expression of AURKA in human breast cancer tissue." (PMID 23186136, 2012). "Several studies have assessed the importance of aurora kinase A and B in breast cancer." (PMID 23186136, 2012). "Indeed, the overexpression of AURKA in breast cancer cells has been reported to increase cell migration through ADF/cofilin pathway." (PMID 22347440, 2012). "Moreover, YTHDF1 suppresses breast cancer apoptosis by m6A-mediated stabilization of aurora kinase A (AURKA) mRNA, while peptidyl-prolyl cis–trans isomerase NIMA-interacting 1 (PIN1) overexpression enhances YTHDF1 stability through inhibition of its degradation." (PMID 40986143, 2025). "Thus, AURKA inhibitors hold great potential in breast cancer therapy." (PMID 40949156, 2025). "AURKA may also attenuate the efficacy of PI3K-pathway inhibitors in breast cancer." (PMID 40949156, 2025). "They observed that, in BRCA2-deficient breast cancer cells, the silencing of either AurkA or TPX2 causes a reduction in cell viability compared to BRCA2-proficient cells, suggesting that the survival of genomically unstable cancer cells depends on the AurkA/TPX2 signalling axis." (PMID 39195284, 2024). "Hence, overexpression of AURKA could lead to dysregulation in the PI3/Akt/mTOR pathway and an increase in EMT factors associated with more aggressive breast cancer." (PMID 38886738, 2024). "In addition, evidence in hormone receptor positive (HR+) breast cancers suggest potential roles for upstream receptor overexpression (FGFR2) and de novo mutations in RAS, AKT1, AURKA, CCNE2, and/or ERBB2 in the activation of ERK following acquired CDK4i/6i resistance." (PMID 38066089, 2024). "In this study, the expression level of AURKA was found to be upregulated in ES, consistent with the results of previous studies that the expression level of AURKA is upregulated in numerous types of cancers, including lung cancer, breast cancer, and gastric cancer." (PMID 38287009, 2024). "However, all three AS isoforms supported equal AURKA protein translation, apparently excluding that exon II could account for AURKA protein overexpression in breast cancers." (PMID 36067794, 2022). "Thus, carvacrol and thymol are potent inhibitors of the AURKA protein in breast cancer." (PMID 36678556, 2022). "Although previous studies in breast cancer cellular models showed that sensitivity to low-dose FTY720 could be predicted by a high mRNA expression of AURKA (unpublished data), this study shows that sensitivity to FTY720 in CRC cell lines cannot be predicted using this model." (PMID 34768523, 2021).
breast cancer (continued). "Furthermore, lapatinib was able to lower the level of AURKA in breast cancer." (PMID 34337875, 2021). "The pathway of extracellular signal-regulated protein kinase (ERK1/2) in cancers, such as breast cancer, squamous cell carcinoma of head and neck cancer, could be activated by AURKA as well, thereby promoting the motility of cancer cells as well as proliferation and growth of cancer." (PMID 34565287, 2021). "A recent study of kinome profiling of breast cancer cell lines using unbiased multiplexed inhibitor beads (MIBs), mass spectrometry (MS) demonstrated that resistance to drugs that target PI3K components, including AKT and mTOR, was associated with a failure to inhibit AURKA." (PMID 33371187, 2020). "Aberrant activity of AURKA facilitates tumorigenic transformation and progression through defective control of the mitotic spindle checkpoint in mammalian cells and in several types of human tumors, including breast cancer, colorectal cancer, myeloid leukemia and hepatocellular carcinoma." (PMID 30547784, 2018). "Thus, studies have indicated AURKA as an important target in breast cancer therapy." (PMID 30104527, 2018). "In addition to the main effects, interaction between HMMR and AURKA, and between HMMR and TUBG1 could influence breast cancer risk in BRCA1 and BRCA2 mutation carriers." (PMID 25830658, 2015). "In this CGH analysis the authors show that, indeed, in breast cancer, there is amplification of the 20q and 16p regions (AURKA and PLK1) whereas the 4q region is often deleted, indicating that downregulation of MAP9 (4q32.1) could be the result, at least in part, of a gene loss." (PMID 24876664, 2014). "AURKA is highly expressed in CSLCs of various tumors, including HCC, breast cancer, ovarian cancer, colorectal cancer, and acute myelocytic leukemia." (PMID 40311679, 2025). "To identify the metabolic indications of AURKA inhibitors, we performed CRISPR/Cas9 screens using the metabolic library in lung and breast cancer cells." (PMID 38521813, 2024). "The interplay between EZH2 and other cell cycle targets (e.g., AURKA, CHEK1, CDKN1A) has also been reported in other contexts such as breast cancer, melanoma, non-Hodgkin’s lymphoma, T-cell acute lymphoblastic leukemia." (PMID 38405800, 2024). "Wang and colleagues illustrated that AURKA stabilises YAP1 and enhances its protein levels in breast cancer models." (PMID 38467828, 2024). "They observed that AURKA elevated the transcriptional activity of E2F1; while both proteins were found to be elevated in breast cancer tissues." (PMID 39598228, 2024). "It was seen through different databases that HMMR was highly upregulated in various malignancies, including breast cancer, and HMMR has a correlation with AURKA, TPX2, and CDK1, which are also involved in the upregulation of mTOR signaling pathways." (PMID 38576486, 2024). "In breast cancer, elevated HMMR activates AURKA and reduces ARPC2 localisation in the mitotic cell cortex, which correlates with micronucleation and the activation of cGAS-STING and non-canonical NF-κB signalling." (PMID 38633247, 2024). "Forkhead box M1 (FOXM1), which along with AURKA is a co‐predictor of prognosis and sorafenib efficacy in HCC, regulates AURKA at the promoter level resulting in increased self‐renewal capacity of breast cancer stem cells." (PMID 38590119, 2024). "This interaction is further strengthened by the direct binding of AURKA to DROSHA, promoting stem cell-like properties in breast cancer." (PMID 39596216, 2024). "The metastasis-related gene MMP11 and proliferation-related genes BIRC5, MYBL2, MKI67 (Ki67), AURKA (STK15), CCNB1, and ERBB2 (HER2) from the Oncotype DX gene set exhibit significant up-regulation in tumor samples of breast cancer (BRCA)." (PMID 38254834, 2024). "However, data on whether Aurora-A/AURKA expression is associated with prognosis specifically in young breast cancer has been lacking." (PMID 39198859, 2024).
breast cancer (continued). "AURKA can also interact and phosphorylate BRCA1 and BRCA2 genes, which are known to promote breast cancer when deregulated." (PMID 38886738, 2024). "For instance, in breast cancer stem-like cells, AURKA strengthens the binding of IGF2BP2 to stabilize m6A-modified DROSHA, resulting in the maintenance of breast cancer stemness." (PMID 38281999, 2024). "YAP1 activation is associated with this resistance, prompting an investigation into AURKA’s role in mediating YAP1 phosphorylation at Ser397, as observed in breast cancer." (PMID 38467828, 2024). "As AURKA is well known for its implication in cancer development, its role in LIMK2 activation will be more extensively discussed in the breast cancer subsection." (PMID 36899941, 2023). "Blocking AURKA nuclear translocation with small molecule drugs partially reversed the oncogenic splicing of RBM4 and GOLGA4 in breast cancer cells." (PMID 37415951, 2023). "Blocking AURKA nuclear translocation with small molecule chemicals partially reversed the oncogenic splicing of RBM4 and GOLGA4 in breast cancer cells." (PMID 37415951, 2023). "In line with our studies, other groups reported that ASPM, KIF20A, TPX2, AURKA and KIF2C are among the top 11 up-regulated hub key genes identified as potential breast cancer prognostic biomarkers." (PMID 37835564, 2023). "Elevated expression of the five hub genes AURKA, BUB1B, CCNA2, CCNB2, and PBK are related to poor OS in breast cancer patients." (PMID 36980449, 2023). "Correlation analysis in GEPIA indicated that AURKA at a high level has linkage to both YBX1 and hnRNPK with increased expression in breast cancer." (PMID 37415951, 2023). "In breast cancer (BC), METTL14 can be stabilized by AURKA by inhibiting proteasomal‐dependent degradation." (PMID 36260366, 2023). "Altogether, these results indicate that AURKA, ATP5F1A, and ATP5F1B cooperate in regulating cell cycle progression and in maintaining total ATP levels in breast cancer cells with high AURKA expression." (PMID 37386025, 2023). "The co-targeting blockade of AURKA and the PI3K signaling pathway is available in the breast cancer models." (PMID 37781397, 2023). "The usage of bioinformatics tolls resulted in the identification of AURKA, AURKB, TTK, MELK and KIF20A as top 5 hub genes involved in breast cancer occurrence and progression." (PMID 37231064, 2023). "AURKA, BUB1B, CCNA2, CCNB2, and PBK, and these hub genes obtained were found to be upregulated (based on log2fold change value) in breast cancer." (PMID 36980449, 2023). "AURKA-mediated phosphorylation is necessary for CIC-related processes, which promotes entosis in breast cancer cells through the regulation of microtubule plus-end dynamics and cell rigidity." (PMID 35974300, 2022). "In breast cancer stem-like cells (BCSC), aurora kinase A (AURKA) binds to IGF2BP2 and strengthens IGF2BP2 to stabilize DROSHA mRNA in an m6A-modified way, thereby increasing BCSC stemness maintenance." (PMID 35541906, 2022). "Aurora kinase A (AURKA) is a member of serine/threonine kinases family and was reported to stabilize METTL14 protein by preventing its ubiquitylation in breast cancer stem-like cells." (PMID 35859892, 2022). "We previously showed that breast cancer cell lines are sensitive to doses of FTY720 between 0.05 μM and 0.1 μM, and that sensitivity can be predicted by overexpression of AURKA (unpublished data)." (PMID 34768523, 2021). "For example, aurora-A kinase (AURKA) is overexpressed in TNBC to mediate TGF-β-induced EMT in docetaxel-resistant and paclitaxel-resistant breast cancer cells." (PMID 34917620, 2021). "Previously, we identified that AURKA directly phosphorylates and degrades PHLDA1 in breast cancer cells." (PMID 34625072, 2021). "In breast cancer stem cells, nuclear AURKA is recruited by FOXM1 and binds to the FOXM1 promoter to transactivate its expression, while FOXM1 activates AURKA expression at the transcriptional level in a similar manner." (PMID 33451333, 2021).
breast cancer (continued). "We have previously shown that breast cancer cell lines are sensitive to the PP2A activator FTY720, and that sensitivity is predicted by high Aurora kinase A (AURKA) mRNA expression." (PMID 34768523, 2021). "We also investigated the correlation between increased AURKA expression and shorter survival of patients with luminal ER+, PR+, HER-2- and basal-like ER-, PR-,HER-2+ breast cancer subtypes." (PMID 33674749, 2021). "An interaction between AURKA (Aurora Kinase A) and MAPK pathway has been proposed for a new treatment strategy using a combination of AURKA and MEK1/2 inhibitors in breast cancer." (PMID 34131308, 2021). "The top three proteins (CKAP5, AURKA, and CDC20) interacting with TACC3 were verified by immunoprecipitation in breast cancer cells, and CKAP5, AURKA, and CDC20 were detected in the immunoprecipitation of anti TACC3 antibody." (PMID 34149795, 2021). "AURKA targeting inhibits self-renewal capacity and restores sensitivity to DTX-based chemotherapy in breast cancer." (PMID 34266348, 2021). "AURKA inhibitors (e.g., MLN8237) were found to synergize with PI3K inhibitors to kill breast cancer cell lines in vitro and in xenograft models." (PMID 33809714, 2021). "In this study, the authors demonstrated that hypoxia downregulated AURKA via a HIF-1α dependent mechanism, suggesting that HIF-1α is a negative regulator of AURKA in breast cancer tumours." (PMID 34062959, 2021). "The positive feedback signaling loop between AURKA and FOXM1 is crucial for breast cancer stem cell self-renewal." (PMID 33451333, 2021). "AURKA attenuates the efficacy of inhibition of the PI3K-AKT-mTOR pathway, a downstream pathway of EGFR, in breast cancer." (PMID 33451333, 2021). "Lastly, we analyzed the prognostic values of AURKA and the OXPHOS-related gene in breast cancer using the Kaplan–Meier plotter database." (PMID 34593753, 2021). "Four kinases-serine/threonine-protein kinase Nek2 (NEK2), aurora kinase A (AURKA), cyclin-dependent kinase 1 and 2 (CDK1 and CDK2) were the predicted to be activated across breast cancer, colon cancer, LUAD, ovarian cancer, and UCEC." (PMID 32033228, 2020). "It was shown that besides p38, MKK3 can bind to multiple other proteins, including several drivers of breast cancer, such as CDK4, AURKA, FGFR4, EPHA2, and MYC." (PMID 32873298, 2020). "Our results indicate that combined inhibition of AURKA and PAK1 is of potential value for the treatment of breast cancer, with greatest efficacy seen in luminal HR + and HER2 + subtypes in vitro." (PMID 31254157, 2019). "Together, our results provide evidence that dual inhibition of AURKA and PAK1 is of value in breast cancer." (PMID 31254157, 2019). "In kinase-independent functions, AURKA interacts with heterogeneous nuclear ribonucleoprotein K to activate C-MYC promoter, enhancing breast cancer stem cell phenotypes." (PMID 31254157, 2019). "The serine-threonine kinases Aurora A (AURKA) and p21-activated kinase 1 (PAK1) are frequently overexpressed in breast tumors, with overexpression promoting aggressive breast cancer phenotypes and poor clinical outcomes." (PMID 31254157, 2019). "Here, for the first time, we evaluated the effect of combining the AURKA inhibitor alisertib and the PAK inhibitor FRAX1036 in preclinical models of breast cancer." (PMID 31254157, 2019). "We have identified three highly connected modules, EED, DHX9, and AURKA, which are extremely activated in TNBC tumors compared to both normal tissues and other breast cancer subtypes." (PMID 31134131, 2019). "In breast cancer, subnetwork modules encompassing proliferation pathways (Mitosis, PLK1, AURKA, and AURKB) were highly prognostic." (PMID 30420699, 2018). "In this article, trans-chalcone and Licochalcone A differentially modulate gene expression in BT-20 (triple-negative) and MCF-7 (responsive hormone) breast cancer, as well as reduced levels of MDR1 and AURKA proteins." (PMID 30104527, 2018).
breast cancer (continued). "We also added genes important for breast cancer biology or subtyping (ER, PGR, ERBB2, MKI67, AURKA and FOXC1)." (PMID 29973242, 2018). "To validate this finding further, we next studied the expressions of AURKA and FOXM1 in primary human breast cancer samples." (PMID 28114286, 2017). "Consistently, breast cancer patient samples portrayed a strong and significant correlation between the expression levels of FOXM1 and AURKA." (PMID 28114286, 2017). "With the increase in our knowledge of aurora kinases, nuclear AURKA has been found to bind to hnRNP K, acting as a transactivating factor to activate the expression of MYC and promoting breast cancer." (PMID 28595628, 2017). "Overexpression of AURKA significantly increased the CD44hi population and the mammosphere formation capacity in MCF-7 breast cancer cells." (PMID 28114286, 2017). "Accordingly, knockdown of AURKA also reduced the CD44hi/CD24lo sub-population and the mammosphere formation capacity in MDA-MB-231 breast cancer cells." (PMID 28114286, 2017). "Next, immunohistochemistry was used to determine protein levels of AURKA and FOXM1 in 269 primary human breast cancer patient samples from Sun Yat-Sen University Cancer Center." (PMID 28114286, 2017). "In this study, we induced ectopic expression of AurkA in MCF-7 cells, a low-aggressive breast cancer cell line with low metastatic potential." (PMID 27341528, 2016). "On AURKA depletion, the putative BCSC CD24low/CD44high cell population was significantly reduced in all breast cancer cell lines." (PMID 26782714, 2016). "To further substantiate the positive regulatory role of nuclear AURKA and hnRNP K in MYC expression and promotion of BCSC phenotype, we isolated primary cells from human breast cancer tissues." (PMID 26782714, 2016). "Here the authors show that in breast cancer cells Aurora kinase A has a kinase-independent function in the nucleus by activating the MYC promoter in cooperation with hnRNP K, enhancing the breast cancer stem cell phenotype." (PMID 26782714, 2016). "Comparison of copy number analysis of HMEC, SUM149PT, SUM1315MO2 adherent cells revealed high copy numbers of AKT1, AURKA, CDK4, EGFR1, PAK1 and MYC in breast cancer cells as compared to HMEC cells." (PMID 26608463, 2015). "AURKA, BIRC5, CCNB1, MKI67 and MYBL2 are well characterized genes involved in breast cancer proliferation." (PMID 22046260, 2011). "AURKA and PLK1 are essential mitotic regulators that promote the G2/M transition and are often overexpressed in aggressive breast cancers, while CDC25C facilitates CDK1 activation and has been associated with unchecked cell cycle progression in high-grade tumors." (PMID 41017855, 2025). "This could be the case of the miR17-92 cluster induced by AURKA, through E2F transcription factor 1 (E2F1) in breast cancer." (PMID 39598228, 2024). "AURKA phosphorylates and activates ERα via LEM4 in ER+ breast cancer cells." (PMID 39334449, 2024). "The five potential prognostic biomarkers, i.e., Aurora Kinase A (AURKA), BUB1 Mitotic checkpoint serine/threonine kinase B (BUB1B), Cyclin A2 (CCNA2), Cyclin B2 (CCNB2), and PDZ binding kinase (PBK) were upregulated in breast cancer." (PMID 36980449, 2023). "Our previous reports indicated that MUC16 could induce the G2-M transition of breast cancer cells by interacting with Janus kinase 2 (JAK2), which in turn enhances the phosphorylation of STAT3 (Y705) and Aurora Kinase A." (PMID 36918912, 2023). "According to prior reports, AURKA in the nucleus performs a function independent of kinase to enhance the phenotype of breast cancer stem cells, where it transactivates target gene expression of MYC and FOXM1." (PMID 37415951, 2023). "Bioinformatic analysis yielded several differentially expressed cell-cycle-related genes, from which we selected Aurora kinase A (AURKA) and topoisomerase IIα (TOP2A) for RT-qPCR and western blot validation in MDA-MB-231 and MCF7 breast cancer cells, as well as normal breast epithelial cells (HMEC)." (PMID 37888205, 2023).